U3 (Small nucleolar RNA U3 )
Synonyms: LOC124904381
Gene: Small nucleolar RNA gene on chromosome 18 (7,995,570 to 7,995,785, forward strand). Ensembl gene ENSG00000199856.
Gene Ontology:
Biological process: RNA processing
Cellular component: nucleolus
Homologues: Orthologues: chimpanzee U3 (99% identical), macaque U3 (93% identical). Paralogues in human: U3 (90% identical), SNORD3P1 (88% identical), U3 (86% identical), U3 (85% identical), SNORD3G (83% identical), SNORD3H (82% identical), U3 (82% identical), U3 (81% identical), SNORD3E (81% identical), U3 (80% identical), SNORD3D (79% identical), U3 (79% identical), and 13 more.